GSTP1 (glutathione S-transferase pi 1)
Diseases named in the same sentence as GSTP1 in open-access papers (continued):
Sharing a sentence is not in itself a finding about the gene and the disease.
melanoma (9 papers, 2005 to 2024). A malignant, usually aggressive tumor composed of atypical, neoplastic melanocytes. "GSTP1, an isozyme that plays an important role in the detoxification of oxidative byproducts generated during melanin synthesis, has been associated with melanoma susceptibility." (PMID 37255601, 2023). "Our study found higher expression of GSTP1 in melanoma samples; elevated GSTP1 expression may be associated with poorer prognosis." (PMID 39439891, 2024). "MC3165 and MC3181, two nitrobenzoxadiazole (NBD) analogs that are orally active and water-soluble, specifically target GSTP1 and can inhibit viability in a panel of human melanoma cell lines and in several human melanoma xenograft models." (PMID 34943045, 2021). "Malignant melanoma is a very chemoresistant tumour, which expresses, in 100% of individuals, high level of GSTP1 and, in about 50% of melanoma specimens, high level of MRP1." (PMID 15999103, 2005). "In fact, as found in melanoma specimens, A375 cells expressed high levels of GSTP1 and MRP1, whereas very lower levels of GSTM1 and MRP3 were detected." (PMID 15999103, 2005). "Taken together, these data strongly suggested a relationship between GSTP1 expression level and etoposide resistance of human melanoma." (PMID 15999103, 2005). "In conclusion, GSTP1 can act in a combined fashion with MRP1 to protect melanoma cells from toxic effects of etoposide." (PMID 15999103, 2005). "In this paper, we examined the effects of the inhibition of GSTP1 expression, by an inducible AS RNA, on drug sensitivity of human melanoma A375 cells in relation with endogenous MRP proteins." (PMID 15999103, 2005). "Importantly, GSTP1 also plays a crucial role in melanoma by augmenting drug resistance and enhancing detoxification mechanisms, thereby positioning itself as a potential therapeutic target." (PMID 39439891, 2024). "To confirm the involvement of functional GSTP1 and MRP1 in the observed resistance of A375 melanoma cell to etoposide, we studied the effects of GSTP1 AS RNA expression, and of pharmacological inhibitors (curcumin, ethacrynic acid, BSO, sulfinpyrazone, MK571), on [3H]-etoposide accumulation." (PMID 15999103, 2005). "Thus, as reported from nontumoral cells the efficacy of the MRP1-mediated protection against etoposide was improved by the expression of functional GSTP1 in human melanoma A375 cells." (PMID 15999103, 2005). "Furthermore, GSTP1-1 is often co-expressedwith the multidrug resistance-associated protein 1 (MRP1) in melanoma, and acts in acombined fashion with this export pump to protect melanoma cells from some cytotoxicagents." (PMID 25595904, 2015). "In addition, the polymorphism GSTP1 rs1695 and the combined GSTM1 and GSTT1 null polymorphisms have been associated with melanoma susceptibility and with further increase in melanoma risk." (PMID 26064422, 2015). "The selective targeting of GSTP1 using 6-(7-nitro-2,1,3-benzoxadiazol-4-ylthio)hexanol (NBDHEX) has shown increased efficiency of chemotherapeutic drugs in melanoma." (PMID 32526885, 2020). "The most promising compound, MC3181,was further studied in vitro both for ability to affect theinteraction between GSTP1-1 and JNK1 or TRAF2, and for antitumor efficacy against apanel of human melanoma cell lines." (PMID 25595904, 2015). "Glutathione-S-transferase Pi1 (GSTP1) and multidrug resistance protein 1 (MRP1) are overexpressed in melanoma, a skin cancer notoriously resistant to all current modalities of cancer therapy." (PMID 15999103, 2005). "To address this question, an inducible AS RNA strategy we used to, in a tetracycline-controlled fashion, specifically inhibit GSTP1 expression in the GSTP1 and MRP1 expressing A375 human melanoma cells." (PMID 15999103, 2005). "In conclusion, we report a combined action of GSTP1 and MRP1 in the protection of A375 melanoma cells from etoposide effect." (PMID 15999103, 2005).
neuroblastoma (9 papers, 2004 to 2023). Neuroblastoma (NB) is the most common solid, extracranial childhood tumor. "Reduced mRNA and protein expression of GSTP1 (glutathione S-transferase-pi) was found in neuroblastoma cell lines and high risk NB tumor samples." (PMID 27206673, 2016). "The development of neuroblastoma may be aided by abnormal GSTP1 methylation, which might also be utilized as a novel diagnostic tool." (PMID 37901797, 2023). "Such GSTP1-1 dependent activation of JNK pathway is well documented in Jurkat, human neuroblastoma cell line, and in NB4 cell line, against variety of chemical exposures." (PMID 21445290, 2011).
triple-negative breast carcinoma (9 papers, 2017 to 2025). An invasive breast carcinoma which is negative for expression of estrogen receptor (ER), progesterone receptor (PR), and human epidermal growth factor receptor 2 (HER2). "Cyclopropenone compounds inhibit the activity of glutathione S-transferase pi-1 (GSTP1) which is one of the triple-negative breast cancer drivers." (PMID 36431829, 2022). "Using a reactivity-based chemoproteomic platform, GSTP1 was identified as a chief player that controls cancer cell metabolism in triple-negative breast cancer cells." (PMID 33946704, 2021). "Elevated levels of GSTP1 are shown in pancreatic and triple-negative breast cancer cells, where it interferes with the cellular signaling processes that influence cell survival, proliferation, and apoptosis." (PMID 33946704, 2021). "In addition, genetic and pharmacological inactivation of GSTP1 in triple-negative breast cancer showed increased phosphorylation of 5′ adenosine monophosphate-activated protein kinase (AMPK) and acetyl-coenzyme A carboxylase." (PMID 33946704, 2021). "GSTP1 directly binds to glyceraldehyde-3-phosphate dehydrogenase (GAPDH) and activates its glycolytic enzyme function in triple-negative breast cancer cells, as demonstrated by pharmacological inactivation." (PMID 34209254, 2021). "Particularly, GSTP1 and GSTM3 have been reported as being dysregulated in cancers such as: prostate cancer, triple-negative breast cancer, lung cancer, and colorectal cancer." (PMID 29774096, 2018). "We analyzed tumors from MDA-MB-231cells a triple negative breast cancer (TNBC), and we did not observe GSTP1 protein expression during TP or changes in tumor growth after treatment with anti-GSTP1 morpholine under our experimental conditions." (PMID 29774096, 2018).
type 2 diabetes mellitus (9 papers, 2015 to 2025). A type of diabetes mellitus that is characterized by insulin resistance or desensitization and increased blood glucose levels. "The rs1695 (Ile105Val) polymorphism is the most studied variant of the GSTP1 gene in a variety of human diseases such as type 2 diabetes, acute lymphoblastic leukemia, Hodgkin’s lymphoma, breast cancer, lung cancer, acute pancreatitis, Alzheimer’s disease, and bronchial asthma." (PMID 36902173, 2023). "GSTP1 polymorphism is associated with susceptibility to type II diabetes mellitus and the risk for developing chronic periodontitis and could similarly imply risk for its analogue peri-implantitis." (PMID 31275749, 2019). "The link between polymorphic genes involved in redox homeostasis, such as GCLM (rs2301022), GGT7 (rs6119534, rs11546155), GSTM1 (+/del), GSTP1 (rs1695, rs1138272), RAC1 (rs7784465), and CYBB (rs5917471), and type 2 diabetes differs in overweight and normal-weight individuals." (PMID 36902173, 2023).
childhood asthma (8 papers, 2008 to 2025). "Our study suggested that low vitamin A intake increased susceptibility to development of ETS-associated childhood asthma by decreasing antioxidant capacity, and the oxidative stress-related GSTP1 gene further modified this association." (PMID 26490046, 2015). "A glutathione gene variant GSTP1 has been linked as a susceptibility gene for childhood asthma." (PMID 22103391, 2011). "Gene polymorphisms in glutathione s-transferase Pi-1 (GSTP1) and catalase (CAT) can modulate the risk of childhood asthma, with certain variants linked to higher risk and others to a protective effect." (PMID 41006975, 2025). "Association analysis results showed that SNPs at GSTP1 gene rs1695, rs4891, HMOX1 gene rs17878790, CAT gene rs7943316, and rs769217 loci are associated with the risk of childhood asthma in Fuzhou region." (PMID 40433469, 2025). "The combination of GSTP1 gene rs1695 and CAT gene rs7943316 formed the best predictive model for assessing the risk of childhood asthma in the Fuzhou region." (PMID 40433469, 2025). "GSTP1 gene SNPs rs1695 A>G, rs4891 T>C, CAT gene SNP rs7943316 A>T are potential risk factors for childhood asthma in the Fuzhou region." (PMID 40433469, 2025). "Discuss the correlation between single nucleotide polymorphisms (SNPs) of the Glutathione s-transferase Pi-1 (GSTP1), Catalase (CAT), Heme oxygenase-1 (HMOX1), and Homo sapiens epoxide hydrolase 1 (EPHX1) genes and the risk of childhood asthma in Fuzhou." (PMID 40433469, 2025). "Of the 27 combinations of three-way gene-gene interaction, GSTP1 GG, IL4Ra GA and INSIG2 GG resulted in the highest risk for childhood asthma." (PMID 22355322, 2012). "To date, there is no research on the association between GSTP1, CAT, HMOX1, EPHX1 gene SNPs and the risk of childhood asthma in the Fuzhou region." (PMID 40433469, 2025). "Moreover, the IL4Ra and INSIG2 gene combination interacted with GSTP1, STAT6, ADRB2, ADRB3, IL13 and EPHX1 exon 3 to reveal a high training-balanced accuracy above 58.38% in childhood asthma." (PMID 22355322, 2012).
Parkinson disease (8 papers, 2010 to 2025). A progressive degenerative disorder of the central nervous system characterized by loss of dopamine producing neurons in the substantia nigra and the presence of Lewy bodies in the substantia nigra and locus coeruleus. "Low levels of GSTP1 have been linked to various neurodegenerative diseases such as Parkinson’s and Alzheimer’s, neurodevelopmental disorders such as autism spectrum disorders and mental illnesses such as schizophrenia and bipolar disorder." (PMID 40051599, 2024). "Decreased expression of Gstp1 has recently been implicated in dopamine neuron degeneration in Parkinson’s disease progression." (PMID 26090715, 2015). "Moreover, pesticide exposure was associated with the Parkinson disease development, which can be potentiated by the I/V genotype of GSTP1-Alw26I." (PMID 40243837, 2025). "Similarly, the heterozygous polymorphism for GSTP1-Alw26I was prevalent in Parkinson disease patients exposed to pesticides." (PMID 40243837, 2025). "In fact, it has been suggested that GSTP1 polymorphisms may also play a role in excessive oxidative stress and the promotion of motor neuron death involved in neurodegenerative disorders such as Alzheimer’s disease and Parkinson’s disease." (PMID 40284160, 2025).
prostate adenocarcinoma (8 papers, 2010 to 2024). "Aberrant DNA methylation of GSTP1 gene associated with inappropriate gene-silencing is an important carcinogenic event in prostate adenocarcinoma." (PMID 25389438, 2014). "For the first time, we report that GSTP1-positive cases are significantly more common in prostatic adenocarcinomas from Black patients compared with White patients (2.5–3 fold)." (PMID 34191807, 2021). "We applied an analytically validated automated IHC assay to evaluate GSTP1 protein expression in a series of TMAs constructed from patients with clinically localized primary prostatic adenocarcinomas." (PMID 34191807, 2021). "A total of 5,757 TMA cores containing prostatic adenocarcinoma from 1,673 patients were evaluable for GSTP1 protein scoring by IHC." (PMID 34191807, 2021). "We used immunohistochemistry against GSTP1 to examine 1673 primary prostatic adenocarcinomas on tissue microarrays (TMAs) with redundant sampling from the index tumor from prostatectomies." (PMID 34191807, 2021). "In comparison to existing tools, MEXPRESS allows researchers to quickly visualize and interpret the different TCGA datasets and their relationships for a single gene, as demonstrated for GSTP1 in prostate adenocarcinoma." (PMID 26306699, 2015). "As an example, the impressive sensitivity and specificity of GSTP1 methylation in prostate adenocarcinoma has led to a variety of studies in its clinical use." (PMID 21063414, 2010). "In summary, we systematically examined GSTP1 protein expression in a large number of primary prostatic adenocarcinomas and found an overall rate of positivity of 7.7%, and a higher percentage of cases staining positive in Black men compared with cases from White men (2.5–3 fold)." (PMID 34191807, 2021). "DNA (cytosine-5-) methylation silencing of GSTP1 function occurs in prostate adenocarcinoma (PCa)." (PMID 25389438, 2014). "Data from The Cancer Genome Atlas Prostate Adenocarcinoma (TCGA PRAD) cohort showed that GSTP1 was methylated in >85% of tumour samples, with concomitant suppression of GSTP1 mRNA expression." (PMID 39744075, 2024). "As expected, carcinoma cells in most prostatic adenocarcinomas were completely negative for GSTP1 protein (92.3%)." (PMID 34191807, 2021).
chronic periodontitis (7 papers, 2014 to 2024). A chronic inflammatory process that affects the tissues that surround and support the teeth. "This study aimed to investigate the distribution of GSTM1, GSTT1, and GSTP1 variants and their roles in periodontitis susceptibility in a Caucasian population." (PMID 38419025, 2024). "The present study aims to determine the association between a genetic polymorphism of GSTP1 (rs1695) and the risk of periodontitis." (PMID 37886736, 2023). "The aim of this study was to determine the frequency of GSTM1, GSTT1, and GSTP1 polymorphisms in Mexicans with chronic periodontitis." (PMID 27350970, 2014). "A recent case-control study in a Pakistani population reported that the absence of GSTM1, the presence of GSTT1, and the mutant allele (G) at rs1695 in the GSTP1 gene may be associated with susceptibility to periodontitis." (PMID 38419025, 2024). "In an investigated set of 201 controls and 203 periodontitis patients, the researchers detected that the absence of GSTM1, presence of GSTT1, and mutant allele (G) at rs1695 in the GSTP1 gene might be associated to susceptibility to periodontitis." (PMID 38419025, 2024). "Importantly, the results of this pilot study comprise the first report of the presence of GSTM1, GSTT1, and GSTP1 polymorphisms in a Mexican population with chronic periodontitis." (PMID 27350970, 2014). "The patients with chronic periodontitis have a higher frequency of null and mutant polymorphisms in GSTM1, GSTT1, and GSTP1 compared with historical data from a healthy Mexican population." (PMID 27350970, 2014). "Weak relationships between GSTT1 and GSTP1 rs1138272 polymorphisms and periodontitis in non-smokers were observed in this study." (PMID 38419025, 2024). "In connection with this fact, the present study was designed to identify the association between rs1695 in GSTP1 gene and periodontitis in patients without any exposure to habits such as smoking or tobacco use." (PMID 37886736, 2023). "In conclusion, within the limitations of this study, the results suggest that compared with historical data from a healthy Mexican population, the population with chronic periodontitis shows an increase in null and mutant polymorphisms in GSTM1, GSTT1, and GSTP1." (PMID 27350970, 2014). "A better understanding of the function of the polymorphic genes GSTM1, GSTT1, and GSTP1 and a better understanding of the disease could contribute to the prevention of chronic periodontitis through personalized recommendations and specific intervention." (PMID 27350970, 2014). "However, the wild genotype of GSTT1 and Ala114Ala variant of the GSTP1 genes were present more frequently in non-smoking periodontitis patients than in non-smoking controls." (PMID 38419025, 2024). "However, a weak relationship between GSTT1 and GSTP1 rs1138272 polymorphisms and periodontitis in non-smokers was observed." (PMID 38419025, 2024). "Their patients with chronic periodontitis had a higher frequency of null and mutant polymorphisms in the GSTM1, GSTT1 and GSTP1 genes as compared with the control Mexican population and it was concluded that the presence of these polymorphisms may be a risk factor for the development of CP." (PMID 36833382, 2023). "Therefore, the aim of this study was to determine the frequency of GSTM1, GSTT1, and GSTP1 polymorphisms in Mexican population of smokers and nonsmokers with chronic periodontitis." (PMID 27350970, 2014). "Polymorphisms in the GSTT1 and GSTP1 genes were not significantly different between smokers and non-smokers; however, the GSTM1(+) genotype was significantly more frequent in smokers with periodontitis (p ≤ 0.05)." (PMID 38419025, 2024). "There was found that periodontitis patients, particularly non-smokers, have altered oxidative stress responses due to GSTM1, GSTT1, and GSTP1 variations." (PMID 39599241, 2024).
endometrial cancer (7 papers, 2014 to 2024). Primary or metastatic malignant neoplasm involving the endometrium (mucous membrane that lines the endometrial cavity). "Some studies have presented an association between GSTP1 gene polymorphisms and increased risk of cancers, including endometrial cancer." (PMID 35893933, 2022). "Endometrial carcinoma is the most common gynecologic cancer in developed countries; curiously a first study reported an association between GSTP1 Ile105Val polymorphism and endometrial carcinoma." (PMID 31357662, 2019). "Similarly, an association between the GSTP1 rs1695 SNP and high Cd levels (OR = 1.05, 95% CI = 1.01–1.13) was found in a case–control study assessing the risk of endometrial cancer." (PMID 39330568, 2024). "Similarly, the invasion potential of pituitary tumors and endometrial carcinomas was linked to reduction of GSTP1 expression and methylation frequency, indicating that epigenetically mediated down-regulation of GSTP1 expression may also contribute to aggressive pituitary tumor behavior." (PMID 25076909, 2014). "Additionally, NAMPT, ENOA, CATD, and GSTP1 were differentially found between endometrial cancer and control samples, enabling the distinction of hyperplasia cases." (PMID 39194522, 2024). "We analyzed whether polymorphisms rs1695 in GSTP1 and rs224589 in SLC11A2 genes are associated with the risk of endometrial cancer." (PMID 35893933, 2022). "Meanwhile, unlike in the present study, the previous meta-analysis did not explore the associations between the GSTP1 Ile105Val polymorphism and the risks of cervical and endometrial cancer." (PMID 28410197, 2017). "In the subgroup analysis by cancer type, the GSTP1 Ile105Val polymorphism did not associate with the risk of ovarian, cervical, or endometrial cancer." (PMID 28410197, 2017). "Tissue collected from stage IA endometrial cancer showed upregulation of the proteins GRP78, GSTP1, ACTG, PDIA3, and ENOA and downregulation of ALBU compared to BEC samples." (PMID 39194522, 2024). "None of the tested genetic polymorphisms (rs1695 in GSTP1 and rs224589 in SLC11A2) were found to be associated with endometrial cancer risk." (PMID 35893933, 2022). "Abnormal methylation of CpG in the promoter regions of GSTP1 and RASSF1A tumor suppressor genes is also an important event in the carcinogenesis process of endometrial cancer, which may affect the invasiveness of the tumor." (PMID 36421781, 2022).